ERICD (E2F1-regulated inhibitor of cell death)
Synonyms: TCONS_00014875; ERIC; formerly LINC01130
Gene: Long non-coding RNA gene on chromosome 8 (140,636,281 to 140,638,283, forward strand). Ensembl gene ENSG00000280303.
Diseases named in the same sentence as ERICD in open-access papers:
ERICD is named in the same sentence as 7 diseases in open-access papers, as found by Europe PMC text mining. Sharing a sentence is not in itself a finding about the gene and the disease. The quoted sentences say what the papers report.
infection (1 paper, 2022). The state of being infected such as from the introduction of a foreign agent such as serum, vaccine, antigenic substance or organism. "We have also shown that the infection of epithelial cells by N. gonorrhoeae leads to significant overexpression of the long non-coding RNAs (lncRNAs), including MALAT1, ERICD, and RP11-510N19.5." (PMID 35456069, 2022).
ERICD also shares sentences with these, for which no sentence is quoted: cancer (5 papers); osteosarcoma (3); tumor (3); bladder cancer (1); bladder urothelial carcinoma (1); lung adenocarcinoma (1).